EGFR (epidermal growth factor receptor)
Diseases named in the same sentence as EGFR in open-access papers (continued):
Sharing a sentence is not in itself a finding about the gene and the disease.
lung cancer (continued). "increased signalling via signal transducer and activator of transcription 3 (STAT3), extracellular regulated kinases (ERK) and epidermal growth factor receptor (EGFR), inactivation of phosphatase and tensin homolog (PTEN) and the ALK mutation in lung cancer." (PMID 28122336, 2017). "In preclinical studies, foretinib significantly increases sensitivity in EGFR mutant lung cancer cells with upregulated HGF and increased MET copy number when added to erlotinib." (PMID 29050231, 2017). "Here we combine a novel EGFR-TKI treatment with thermal therapy to improve lung cancer treatment outcomes." (PMID 28915593, 2017). "On one hand, EGFR promotes Nrf2-activated cell proliferation in lung cancer cells through its downstream MAPK/Erk signaling pathway." (PMID 28501854, 2017). "A phase I trial of 173 patients with EGFR-mutant lung cancer that had failed previous TKI therapy demonstrated a favorable safety profile and promising antitumor activity." (PMID 28620581, 2017). "This is surprising as in the treatment of lung cancer both, the EGFR (as a target) as well as platinum-based anticancer drugs, are of high importance." (PMID 28405842, 2017). "In advanced lung cancer, epidermal growth factor tyrosine kinase inhibitors (EGFR TKIs) have extraordinary clinical efficacy." (PMID 29238696, 2017). "It is therefore important to understand the occurrence of EGFR and KRAS mutations when deciding the initial treatment for lung cancer." (PMID 28422979, 2017). "Resistance mechanisms are being identified to these novel agents, and the treatment landscape of EGFR-mutant lung cancer continues to evolve." (PMID 28620581, 2017). "We have provided evidence indicating that Shp2 knockdown reduces the proliferation and migration of lung cancer cells and that co-inhibition of EGFR and Shp2 can effectively overcome acquired EGFR-TKIs resistance." (PMID 29207630, 2017). "Epidermal growth factor receptor (EGFR) tyrosine kinase inhibitors (TKIs) have changed the treatment strategy for EGFR‐mutant lung cancers; however, resistance usually occurs due to a secondary mutation, T790M, in EGFR." (PMID 28388009, 2017). "In fact, the crosstalk between EGFR and MET maximizes the oncogenic activity of EGFR and leads to increased migration and invasion of lung cancer cells." (PMID 28420162, 2017). "Some studies showed lung cancer cell lines regained susceptibility to EGFR-TKI after resting for a period, and this was called EGFR-TKI holiday." (PMID 28486985, 2017). "This study demonstrated that YAP1 is an important EGFR downstream signaling molecule that is crucial for lung cancer cell proliferation." (PMID 29163769, 2017). "Given the resistance to EGFR tyrosine kinase inhibitors in cMET-expressing lung cancer and the synergistic effect of cMET and EGFR inhibitors, dual targeting of EGFR and cMET is a promising therapeutic strategy." (PMID 28336955, 2017). "Although the locations of most of these mutations were not necessarily found on the exact same genomic loci of well-known oncogenes (for example, EGFR L858R for lung cancer), several of them were on important functional domains." (PMID 28240289, 2017). "HDAC inhibitors were also shown to induce E-cadherin in lung cancer and this restoration increased sensitivity to EGFR inhibitors." (PMID 28672805, 2017). "As TSACP panel covers 48 oncogenes and tumor suppressor genes, we were able to extend the analysis of 26 FFPE lung cancer specimens beyond EGFR gene." (PMID 28137276, 2017). "A similar response pattern was observed in a human lung cancer-derived cell line (BID007) harboring EGFR A763_Y764insFQEA." (PMID 29285266, 2017). "The EGFR T790M variation is well studied in lung cancer and is known to confer EGFR-inhibitor resistance." (PMID 28489587, 2017). "EGFR‐mutant lung cancer frequently leads to the development of brain metastases, compared with non‐small‐cell lung cancer (NSCLC) containing a wild‐type copy of EGFR29." (PMID 29125233, 2017).
lung cancer (continued). "An additive effect of the ER antagonist and the epidermal growth factor receptor (EGFR) antagonist on the inhibition of lung cancer cell migration was also observed." (PMID 28783064, 2017). "Both stemness models were used to investigate the cellular stemness property of EGFR-positive lung cancer." (PMID 28787001, 2017). "Therefore, in this study, we determined whether EGFR mutations, including the exon 19 deletion and L858R point mutation subtypes, predict the occurrence of the SBM in NSCLC patients, and characterized the role of activating EGFR mutations in lung cancer cell dissemination." (PMID 28881820, 2017). "As a matter of fact, HER3-mediated resistance to EGFR inhibition with gefitinib has been described in lung cancer cells." (PMID 28032592, 2017). "The authors showed that tumors such as head and neck, renal, and lung cancer, are highly affected by EGFR overexpressing mechanisms, in percentages between 80–100% for head and neck cancer, 50–90% for renal cancer, and 40–80% for lung cancer." (PMID 29271876, 2017). "Treatment outcome in EGFR-mutant NSCLC has been shown to outperform that in other lung cancers owing to the efficacy of EGFR tyrosine kinase inhibitors (EGFR-TKIs)." (PMID 29296194, 2017). "Conversely, restricting ROS generation and/or targeting YY1 in lung cancer cells effectively inhibits the EGFR-MnSOD signaling pathway and cell invasiveness induced by MCT-1." (PMID 28394354, 2017). "As platinum(II) drugs are still the most important therapeutics against lung cancer, we synthesized in this study the first platinum(IV) complexes coupled to the EGFR-targeting peptide LARLLT (and the shuffled RTALLL as reference)." (PMID 28405842, 2017). "Several studies demonstrated the promising application of 18FDG PET in the early evaluation of lung cancer treated with epidermal growth factor receptor (EGFR) TKI, with varied evaluation time, even as early as 2 days after drug administration." (PMID 28178685, 2017). "The Phase III SOLAR study is underway comparing initial ASP8273 with a first-generation TKI in patients with EGFR-mutant lung cancer (NCT02588261)." (PMID 28620581, 2017). "This suggests that the triplet therapy has difficulty overcoming osimertinib resistance in lung cancer harboring EGFR T790M." (PMID 28388009, 2017). "Further research is warranted to elucidate the precise mechanisms for the capacity of Met to enrich EGFR WT lung cancer cells and to enhance the signaling potential of EGFR WT thus more sensitive to the inhibitory effect." (PMID 29312591, 2017). "Commonly, patients with EGFR mutant lung cancers become resistant to first-line EGFR-targeted therapies due to the acquisition of a gatekeeper mutation in EGFR, T790M." (PMID 28431544, 2017). "Erlotinib is a tyrosine kinase inhibitor that acts on the epidermal growth factor receptor; however, it is unclear how this drug is histologically distributed in lung cancer." (PMID 28974758, 2017). "Despite this, EGFR TKI have shown significant benefit compared to placebo in patients with advanced lung cancer (all genotypes) having progressed on first or second-line chemotherapy, including SCC." (PMID 28396848, 2017). "In this study, we observed that YM155 inhibited EGFR autophosphorylation and G9a expression, rendering it a potent agent against lung cancer stemness." (PMID 28787001, 2017). "Consistent with this, we found that EGF stimulation increases CDCP1 expression and EGFR inhibitor reduces the level of CDCP1 in lung cancer cells." (PMID 28537886, 2017). "YM155 efficiently inhibited EGFR autophosphorylation and the EGFR-mediated G9a stemness pathway simultaneously, thus rendering it a potential agent against lung cancer stemness." (PMID 28787001, 2017).
lung cancer (continued). "Approximately 20% of lung cancer patients can actually be stratified for treatment with EGFR targeting therapies that successfully suppress cell growth and promote cell death." (PMID 28978141, 2017). "Recent work also shows that AMPK activation sensitizes EGFR wild type H1299 cells and tumors to erlotinib treatment, suggesting a role of AMPK activation in modulating EGFR signaling and drug sensitivity in lung cancer cells." (PMID 28423657, 2017). "This includes detecting the emergence of EGFR T790M in plasma of patients with EGFR mutant lung cancers treated with erlotinib, which accounts for the majority of treatment failures." (PMID 28392802, 2017). "(2017) Treatments for EGFR‐mutant non‐small cell lung cancer (NSCLC): The road to a success, paved with failures." (PMID 29055036, 2017). "Polycefin nano drug variants were also engineered to treat human Epidermal Growth Factor Receptor (EGFR)-positive lung cancer, triple negative breast cancer, and HER-2/neu positive breast tumors in nude mice." (PMID 28457227, 2017). "MMP‐13 cleaved Ln‐5 into small fragments, thereby abrogating the EGFR signal that disrupts the formation of VM patterns in lung cancer." (PMID 28766880, 2017). "EGFR antibody or affibody can be used for EGFR-targeted delivery of therapeutics to lung cancer cells." (PMID 28290155, 2017). "Designed pipeline was applied to the EGFR-ex20 gene fragment library preparation procedure for the four circulating cell-free DNA samples of patients with lung cancer together with the control for assessment of NOPE-R3 efficiency." (PMID 28583065, 2017). "Conversely, it has also been shown that patients with the mutant EGFR lung cancers rarely respond to EGFR TKIs and are more likely to benefit from chemotherapy, underlining the importance of matching tumor genotype to therapy." (PMID 28430586, 2017). "Elrotinib acts as an inhibitor of epidermal growth factor receptor (EGFR), which works effectively for lung cancer cells." (PMID 28587314, 2017). "EGFR-tyrosine kinase inhibitors (TKIs) offer better efficacy and quality of life for lung cancer patients, and have hence emerged as an important frontline therapy for patients with EGFR-mutant, non-small cell lung cancer." (PMID 29228697, 2017). "As seen with vemurafenib treatment in melanoma or with EGFR inhibitors in lung cancer, acquired resistance will likely arise." (PMID 28145866, 2017). "In lung cancer, especially in NSCLC, a variety of EGFR mutations exist which are closely related to tumor development." (PMID 28430586, 2017). "The observed EGFR L747* in MSI-H CRC involves a hotspot that is frequently involved in lung cancer as various small in-frame deletions leading to kinase activation and sensitivity to TKI therapy." (PMID 28591715, 2017). "The combination of statin and EGFR-TKI in patients with lung cancer was also beneficial in clinical studies." (PMID 28158206, 2017). "As shown in our data, the growth of lung cancer cells is more sensitive to SCD1 inhibitors when EGFR is activated, which is consistent with previous finding that SCD1 activity is more essential for the cells with faster growth rate." (PMID 28724430, 2017). "Some reports have shown that EGFR expression in lung cancer is related to poor chemosensitivity and a reduced survival rate." (PMID 28290155, 2017). "Our study uncovers a novel mechanism that EGFR directly up-regulates intracellular MUFA synthesis through phosphorylating SCD1 at Y55 to promote lung cancer growth." (PMID 28724430, 2017). "As a result, infrastructure for widespread somatic HRD testing in routine clinical practice, as is the case for HER2 in breast cancer and epidermal growth factor receptor in lung cancer, should be supported." (PMID 28250960, 2017). "designed the cetuximab-modified mesoporous silica nanoparticles (MSNs) as the drug carrier to specifically target EGFR-mutant lung cancer cells and efficiently release loaded drugs DOX and gefitinib." (PMID 29191057, 2017).
lung cancer (continued). "The lncRNA UCA1 levels were higher in lung cancer tissues from patients with acquired resistance to EGFR-TKIs compared to EGFR-TKI sensitive patients or patients with primary resistance to EGFR-TKIs." (PMID 28969100, 2017). "For example, UCA1, BC087858 and GAS5 are associated with resistance to EGFR tyrosine kinase inhibitors (EGFR-TKIs) in lung cancer possibly through the Akt signaling pathway." (PMID 28672805, 2017). "The combination of EA1045 and cetuximab blocked the growth of mouse models of lung cancer harboring EGFR T790M and C797S." (PMID 29371993, 2017). "Among treatment modalities for lung cancer, the most promising therapy is the use of epidermal growth factor receptor tyrosine kinase inhibitors (EGFR‐TKIs)." (PMID 28639751, 2017). "This study investigated the effect of statin use among patients with lung cancer receiving epidermal growth factor receptor-tyrosine kinase inhibitor (EGFR-TKIs) therapy." (PMID 28158206, 2017). "In the 141 lung cancer cases divided into pre- (n = 31) and post- (n = 110) EGFR-TKI therapy, we found that the VAF distributions at the hotspots were significantly different (P = 0.018), mostly due to EGFR T790M." (PMID 29123093, 2017). "In lung cancer, primary resistance to EGFR- or ALK-targeted tyrosine kinase inhibitors is a result of genetic alterations in or outside of the primary target." (PMID 28685150, 2017). "In summary, our study demonstrated that the LXR agonist T0901317 sensitizes EGFR‐TKI‐resistant human lung cancer cell A549 to EGFR‐TKI treatment in vitro, and this effect was partly achieved by inhibition of the PI3K/Akt signaling pathway." (PMID 28097086, 2017). "The multivariate analysis showed never-smoker smoking status was the only significant factor for EGFR mutation, and that current and former smoker status was the only significant factor for KRAS mutation in lung cancer." (PMID 28881771, 2017). "It has also been observed that restoring E-cadherin expression increased sensitivity to epidermal growth factor receptor inhibitors in lung cancer cells, while mesenchymal-like cells were resistance to drug treatment." (PMID 28134289, 2017). "Conversely, the incorporation of core fucose by Fut8 promoted EGFR dimerization and phosphorylation in lung cancer cells." (PMID 28912543, 2017). "In summary, we have established an in vivo imaging system for brain tumor models of EGFR‐mutant lung cancers, HGF‐dependent gastric cancers, and NTRK1‐fusion‐positive colon cancers." (PMID 29125233, 2017). "Subset analysis of the small proportion of patients with EGFR-mutant lung cancer showed a disease-free survival benefit, but was underpowered to detect a survival advantage." (PMID 28430586, 2017). "For instance, EGFR × c-MET bispecific antibody JNJ-61186372 enhanced the killing of EGFR mutant lung cancer cells." (PMID 28931402, 2017). "The concordance rate of EGFR copy number in metastatic lymph nodes or recurrent OSCC from our study were within the range of concordance rates for lung cancer." (PMID 28854970, 2017). "The results of a previous study indicated that EGFR T790M mutations can lead to TKI resistance and are positively associated with lung cancer recurrence." (PMID 29132432, 2017). "Although KRAS mutation has been established as a potential biomarker for predicting the efficacy of erlotinib in lung cancer, little is known about a predictive marker for EGFR TKIs in HNSCC." (PMID 28134774, 2017). "In this study, we validated that cancer stemness, as measured using Oct4 expression, was regulated by G9a in the temporary stemness status derived from EGFR-positive lung cancer cells, which was the EGFR-downstream protein serving as a therapeutic target." (PMID 28787001, 2017).
lung cancer (continued). "Specifically, a monoclonal antibody against ErbB2, trastuzumab, and a tyrosine kinase inhibitor against EGFR, gefitinib, have improved the survival of breast and lung cancer patients." (PMID 28338617, 2017). "We have established an in vivo imaging model for brain tumors for the epidermal growth factor receptor (EGFR)‐mutant lung cancer, the HGF‐dependent gastric cancer, and for colorectal cancer harboring the NTRK1 gene fusion." (PMID 29125233, 2017). "Our results validate that miR-107-5p functions as a tumor suppressor through EGFR, and this shed light on precision medicine of lung cancer." (PMID 28915650, 2017). "To date, few targeted therapies and CT regimens have been reported for adenoCA (WT EGFR) or squCA lung cancer." (PMID 27835914, 2017). "This review focuses on the clinical application of liquid biopsies to lung cancer genotyping, including EGFR and other targets of genotype-directed therapy and compares multiple platforms used for liquid biopsy." (PMID 28099915, 2017). "PTPN13 restrained anchorage‐independent growth and tumorigenicity in lung cancer via inactivation of the EGFR and HER228, participated in the lung cancer invasion and negatively correlated with cancer grade and stage 29." (PMID 28653805, 2017). "This study was aimed at bringing further insight into general mechanisms of AQR in the context of the application of PI3K/mTOR inhibitors to EGFR inhibitor-refractory lung cancer." (PMID 29299135, 2017). "We analyzed NEU3 and EGFR mRNA levels using qPCR, by comparing mRNA levels in lung cancer cells with those observed in the healthy HSAEC1 lung cell line." (PMID 29088281, 2017). "In conclusion, our study showed that the use of statins potentially enhances the therapeutic effect and decreases mortality in patients with lung cancer receiving EGFR-TKIs therapy." (PMID 28158206, 2017). "In summary, our functional genomics screen indicated that expression of miR-372 and other AAGUGC-containing miRNAs in lung cancer cells results in increased proliferation and increased sensitivity to EGFR inhibitors." (PMID 27477696, 2017). "In the current targeted therapy era, information on the effect of smoking in epidermal growth factor receptor (EGFR)-mutant lung cancer patients is scarce." (PMID 29228697, 2017). "In this study, we have established in vivo imaging models for brain tumors that mimic brain metastases for EGFR‐mutant lung cancer, HGF‐dependent gastric cancer, and NTRK1‐fusion‐positive colon cancer." (PMID 29125233, 2017). "Mutations subsequently reemerged along with drug resistance mutations after continued treatment with erlotinib in patients with EGFR‐mutant lung cancer." (PMID 28382702, 2017). "In this work, we investigate the effect of sialidase NEU3 overexpression on EGFR pathways activation and EGFR targeted therapies sensitivity, in a series of lung cancer cell lines." (PMID 29088281, 2017). "We next investigated the mechanisms why Met can sensitize human lung cancer cells bearing EGFR WT to the cytotoxicity of Erlo." (PMID 29312591, 2017). "A nationwide population-based study was conducted to determine the effect of statin use in patients with lung cancer receiving EGFR-TKI therapy." (PMID 28158206, 2017). "Till today, we have only limited data concerning the evaluation of the most frequent mutations in EGFR, KRAS, BRAF genes in CNS metastases of lung cancer (especially AC type)." (PMID 28097440, 2017). "Here we describe a similar transformation of LysRS due to EGFR signaling activation in human lung cancer." (PMID 29029422, 2017). "Because KRAS is an effector of EGFR, the EGFR-RAS-RAF-MEK-ERK cascade is considered a target-rich environment for medical management of lung cancer." (PMID 29088821, 2017). "We previously demonstrated that the LXR agonist can sensitize the acquired EGFR‐TKI resistant human lung cancer cells HCC827 by inhibiting Akt activation." (PMID 28097086, 2017).